CTTN (cortactin)
Diseases named in the same sentence as CTTN in open-access papers (continued):
Sharing a sentence is not in itself a finding about the gene and the disease.
cancer (continued). "However, the ORAOV1 gene was identified within chromosomal band 11q13, which includes several known cancer-related genes such as CCND1, FGF4, FGF3, and CTTN." (PMID 24930674, 2014). "This series of data also showed that CTTN mRNA expression level of cancer embolus or metastasis group (Y) was higher than no cancer embolus and metastasis group (N) and control group (C)." (PMID 23518204, 2013). "Cancer cells rely on invadopodia to initiate invasive activity, as these formations are enriched with actin filaments (F-actin) and components needed for actin assembly, including neural-Wiskott Aldrich Syndrome protein (N-WASP) and cortactin." (PMID 23289900, 2013). "EZR is overexpressed in many cancers, including PDAC, even in PanIN lesions, and it interacts with cortactin to form podosomal rosettes in PDAC cells, which may play an important role in tumor invasion." (PMID 24010981, 2013). "Moreover, in both angiogenesis and cancer invasion/metastasis, AMAP1 functions by forming a complex with cortactin." (PMID 21858086, 2011). "Like cancer invasion and metastasis, AMAP1 functions by binding to cortactin in angiogenesis." (PMID 21858086, 2011). "We mimicked 11q13 amplification by generating MMTV-cortactin/-MMTV-cyclin D1 bitransgenic mice but did not observe any synergistic effect of cortactin on cyclin D1-induced mammary hyperplasias or carcinomas, nor development of distant metastasis." (PMID 16536875, 2006). "Finally, both cortactin and HS1 can accumulate into podosomes, structures found in osteoclasts and marcrophages, but also in RSV transformed cells and carcinoma cells." (PMID 15710041, 2005). "Cortactin, along with Ezrin, two distinct cytoskeletal organising proteins, are critical in the formation of cellular processes in PDAC, which may aid in invasion and metastasis of cancer cells." (PMID 39849106, 2025). "CTTN exon 11 inclusion was detected both in the TCGA database and our cohort, and it was co-regulated by survival-related SFs, which may contribute to EMT and cancer stemness." (PMID 40282339, 2025). "Deregulated proteolysis might increase cortactin protein stability in cancer with high cortactin expression but without gene amplification." (PMID 30976201, 2019). "Cortactin, a critical component of invadopodia, frequently used as an invadopodia marker, a universally important player in invadopodia function, and is frequently overexpressed in cancer, but the exact mechanism of regulation is not yet fully understood." (PMID 29986736, 2018). "However, the structural and functional requirement for Hax-1 in Rac1-cortactin mediated signaling machinery involved in cell migration - especially with reference to cancer cell migration and metastasis - has not been fully understood." (PMID 25053987, 2014). "Hence, we postulated that disruption of CTNND1-cortactin interaction may be secondary to curcumin-induced dephosphorylation of cortactin by PTPN1 and may contribute to its effects of curcumin on cancer cell migration." (PMID 24465712, 2014). "To mimic the 11q13 amplification, as seen in several human cancers, and to investigate the involvement of cortactin in mammary gland tumorigenesis and a possible cooperative action of cortactin and cyclin D1, we generated MMTV-cortactin transgenic and MMTV-cyclin D1/-cortactin bitransgenic mice." (PMID 16536875, 2006). "Interestingly, kinome and transcriptome analysis revealed that all components of the EGFR-Pyk2-Src-Arg-cortactin axis are activated following HCV infection, suggesting that this pathway may be a general mechanism for invadopodia-mediated invasiveness of cancer cells." (PMID 34440806, 2021). "The discovery that cortactin/N-WASP controls the Arp2/3 complex via thyroid hormones may thus offer novel insights to better understand the action of these hormones on BC metastasis, although there is considerable evidence of the role of TH in enhancing metastasis in several types of cancer." (PMID 30899247, 2019).
cancer (continued). "In addition, cortactin has been shown to be crucial for trafficking the key invadopodia proteases, including matrix metalloproteinase 1 (MMP1), MMP2, and MMP9 from late endosomes to the plasma membrane, which play a crucial role in the invasive potential of cancer cells." (PMID 29152154, 2017). "Taken together, our cohort of multiparous MMTV-cyclin D1 mice was less potent in promoting mammary hyperplasias and carcinomas as has previously been shown and MMTV-cortactin did not accelerate the incidence of hyperplasia or MG tumors in bitransgenic mice." (PMID 16536875, 2006). "Although a significant correlation between the expression of KCNA3 and of some of the interactors could be observed in all three types of cancers, the only protein whose expression negatively correlated with KCNA3 in SKCM and LUAD but not in LUSC, was cortactin." (PMID 36978819, 2023).
tumor (166 papers, 2006 to 2026). "Our results suggest that p190A regulates the function of the actin-binding proteins cofilin and cortactin in the bladder epithelium and plays a role in maintaining cell ploidy while its loss promotes tumor initiation and progression." (PMID 41253923, 2025). "CTTN, which is in this region, has been identified as a putative promoter of tumorigenesis and is mainly involved in processes underlying tumor progression, such as cell migration, invasion, and tumor metastasis." (PMID 36831511, 2023). "Not surprisingly, the low expression of FAK, paxillin, vinculin, and cortactin predicts good survival outcomes, considering that several studies report an association between their overexpression and tumor aggressiveness." (PMID 37686651, 2023). "Cortactin is an actin binding protein involved in cytoskeletal remodeling and implicated in tumor invasion and WNT-dependent synaptic plasticity." (PMID 35440587, 2022). "Cortactin is an actin related protein 2/3 complex-activating and filamentous (F)-actin-binding protein that is implicated in tumor cell motility and metastasis." (PMID 32029709, 2020). "It has also been reported that CTTN is associated with tumor progression and poor prognosis in many malignancies." (PMID 30220969, 2018). "Through extensive mass spectrometry we identified the proto-oncogene PBF as a new binding partner of CTTN—a critical regulator of actin-cytoskeletal dynamics and associated with tumor aggressiveness." (PMID 27603901, 2016). "In adenocarcinomas of the pancreas and ampulla of Vater, overexpression of Cortactin (and Fascin-1) is associated with poor tumor differentiation, advanced tumor stage, and shorter survival." (PMID 26345720, 2015). "Cortactin overexpression was also associated with higher histologic grade as 44 out of 77 cortactin-overexpressing tumours were poorly differentiated (P=0.001)." (PMID 18268492, 2008). "However, other studies showed that high cortactin expression was significantly associated with larger tumor size and higher TNM stage." (PMID 40217339, 2025). "Cortactin, a family of actin‐binding proteins, is also known to promote invasive protrusions and degrade extracellular matrix in cancer cells, which is associated with tumor metastasis and poor prognosis." (PMID 41365610, 2025). "Moreover, Cortactin, a biomarker associated with tumour metastasis, is found to be upregulated in various tumours including head and neck squamous cell carcinoma and colorectal cancer (CRC), promoting CRC cell proliferation." (PMID 39354653, 2025). "In addition to clinical conclusions such as the predictive association of cortactin overexpression with prognosis, a previous study has shown that overexpression of cortactin causes tumor cell proliferation in vitro." (PMID 37761244, 2023). "Furthermore, PODXL knockdown cells exhibit significantly diminished tumour migration, invasion, as well as proliferation and colony formation, indicating that PODXL expression is associated with tumour aggression through FAK/paxillin/cortactin signalling." (PMID 34201212, 2021). "Therefore, the CTTN expression in association with histologic grade and tumor size of BrCa is largely missing." (PMID 33407452, 2021). "Summarized, persistent canine distemper virus infection induces reduced tumour cell migration associated with an altered intracellular cortactin distribution, indicating cytoskeletal changes as one of the major pathways of virus-associated inhibition of tumour spread." (PMID 27911942, 2016). "However, Cortactin expression showed an association with poor tumor differentiation, more advanced tumor, lymph node and metastasis (TNM) stage, tumor recurrence, and poor survival in GAC in other studies." (PMID 26345720, 2015). "Hence, patients with cortactin-overexpressing tumours displayed a five-fold increase in the risk of local recurrence and nearly a three-fold increase in risk of death by any cause." (PMID 18268492, 2008).
tumor (continued). "Finally, a tumor-promoting role for Calreticulin has been shown to be linked to dysregulation of Cortactin expression, and vascular endothelial growth factor C (VEGF-C) contributes to tumor growth and metastasis via Src-miR326-mediated overexpression of Cortactin in ESCC." (PMID 26345720, 2015). "Most findings support a tumor-promoting function for Cortactin that might be linked to the essential role of the protein in invadopodia formation and maintenance, but the results for class I NPFs (N-WASP/WAVE), Abi1/2, and Cofilin are conflicting, especially in upper gastrointestinal tract tumors." (PMID 26345720, 2015). "Notably, the increased tumor aggressiveness has been associated with increased expression or altered localization of other actin-binding proteins such as β-catenin, actinin-4, cortactin and fascin at the invasive region of tumors." (PMID 22927998, 2012). "As regulators of branched actin assembly, the Arp2/3 complex and cortactin are thought to contribute to sEV secretion in tumour cells by mediating MVB intracellular transport and plasma membrane docking." (PMID 41025959, 2025). "On serial tissue sections, colocalization of Cortactin/E‐cadherin and Cortactin/Tks5 was observed at tumour cell plasma membranes in close contact with the microenvironment." (PMID 40366255, 2025). "FMRP promotes tumor invasion by stabilizing mRNAs of invasion-related proteins, including Cortactin (CTTN), Matrix Metalloproteinase 1 and 9 (MMP1/9), and Proto-oncogene Tyrosine-protein Kinase Src (SRC)." (PMID 40563420, 2025). "Cytoplasmic HDAC6 has been shown to interact with proteins such as α-tubulin, cortactin, heat shock protein 90, β-catenin, and peroxiredoxins, playing a role in the regulation of apoptosis, tumor growth and migration." (PMID 39958888, 2025). "HDAC6 is a member of the HDAC family that is mainly located in the cytoplasm and promotes tumor cell migration and invasion through deacetylation of α‐tubulin and cortactin, which destabilizes the cytoskeleton." (PMID 38334007, 2024). "For example, CCND1 and CTTN showed amplification in more than 9 tumor foci, while CDKN2A and CDKN2B exhibited deletion in more than 6 tumor foci." (PMID 38956687, 2024). "We conducted a comprehensive bioinformatic analysis to investigate the mRNA and protein expression levels of Tks4 and its associated partner molecules (CD2AP, GRB2, WASL, SRC, CTTN, and CAPZA1) across different tumor types." (PMID 39234565, 2024). "The phosphorylation level of cortactin was positively correlated with the expression of SAMHD1 in tumor tissues." (PMID 37009792, 2023). "Our findings showed that CTTN enhances tumor initiation and increases anti-HER2 drug resistance by activating the DKK-1/Wnt/β-catenin signaling pathway." (PMID 36831511, 2023). "Cortactin regulates invadopodia formation by binding and activating the Arp 2/3 complex, thereby promoting cell motility and tumor metastasis." (PMID 37761244, 2023). "Conversely, tumor-free rates were significantly elevated in mice harboring CTTN-knockdown HCC-1954 cells (p = 0.001)." (PMID 36831511, 2023). "In accordance with current literature, we observed a significant overexpression of CTTN in our tumor samples, comparing it to the healthy mucosa samples." (PMID 37623256, 2023). "This idea is further supported by recent studies indicating that CD44 enables invasive tumour cells to produce functional invadopodia by promoting the phosphorylation of cortactin and recruiting MT1-MMP." (PMID 37596406, 2023). "Given the heterogeneity of HNSCC tumor cells, we evaluated amplification rates of ARGs and discovered that FADD and CTTN were often amplified in HNSCC tumor cells." (PMID 37682196, 2023). "We also examined tumor-free rates in xenografted mice and noted a significant reduction in tumor-free rates in mice harboring CTTN-overexpressing SKBR3 cells (p = 0.048)." (PMID 36831511, 2023).
tumor (continued). "According to the literature, overexpression of cortactin is related to tumor invasion and metastasis, and has been reported to be associated with poor prognosis." (PMID 37761244, 2023). "It has been shown that cortactin can change the structure of the cytoskeleton and promote the formation of invadopodia, thereby promoting the invasion and metastasis of tumor cells." (PMID 37686118, 2023). "After the knockdown of CTTN by CTTN RNA interference (RNAi), changes in tumor cell invasive and migratory abilities, pseudopodia, and Rac1 protein expression were observed, and the invasion and migration mechanisms of EC cells were studied." (PMID 37970440, 2023). "Second, colocalization of TKS5 and cortactin has been used to detect invadopodia in xenografted tumor." (PMID 35773411, 2022). "The CTTN levels correlate with increased levels of CREB1 as well as CREB1 downstream signaling toward tumor promotion and cell invasiveness." (PMID 35252867, 2022). "The results indicate the expression of CTTN in tumor tissues was significantly higher than that of normal esophageal tissues." (PMID 35121801, 2022). "CTTN phosphorylation promotes actin polymerization, tumor cell movement, and binding to FAK to activate cell scattering." (PMID 35562995, 2022). "Tumor DNA analysis revealed (a) an EPHA2 G391R variant, which causes continuous activation of EPHA2, with increased phosphorylation of Src, cortactin, and p130." (PMID 33466719, 2021). "It has been found in those studies that cortactin exhibited a high expression trend in various tumours and promoted tumour metastasis." (PMID 33191645, 2021). "Studies have shown that cytokines hepatocyte growth factor (HGF), epidermal growth factor (EGF), etc can enhance the phosphorylation of cortactin, promoting the tumour metastasis." (PMID 33191645, 2021). "It has been found that KDELR2 stimulates ECM degradation by inducing Src activation at the invadopodia and leads to phosphorylation of the Src substrates, cortactin, thereby promoting tumor metastasis and invasive growth." (PMID 34093830, 2021). "This supports the model of an EGFR-Src-Arg-cortactin pathway for invadopodium maturation and activation and consequent tumor cell invasiveness." (PMID 34440806, 2021). "In non-small cell lung cancer (NSCLC), miR-182 was found to target invadopodia formation-related protein CTTN and generate a tumor suppressing function." (PMID 34290983, 2021). "Here, we demonstrated that cortactin was markedly increased in UCEC tumor tissues, and especially exhibited in gland duct cells." (PMID 35178403, 2021). "The results showed that two cortactin-encoding genes, CTTN and HCLS1, were markedly increased in tumor tissues." (PMID 35178403, 2021). "This is the first study to indicate the higher mRNA expression levels of CTTN in significant correlations with larger tumor size and histologic grade II of primary BrCa." (PMID 33407452, 2021). "cortactin acts as a marker for cellular pseudopods, whereas its activation is an important marker of tumour metastasis." (PMID 33191645, 2021). "The DTHL motif of PODXL is further shown to regulate cortactin and Rac1/Cdc42 activation to enhance tumour metastasis and invadopodia formation." (PMID 34201212, 2021). "The interaction of ezrin with cortactin is a new mechanism involved in the EMT during the tumor metastasis process." (PMID 33195233, 2020). "Cortactin participates in tumor proliferation, migration, and invasion and other related disease processes by binding to different proteins and participating in different pathways and mechanisms that induce the occurrence of these disease processes." (PMID 33195233, 2020). "CTTN gain/ increased expression alone has been associated with ESCC metastasis and functional studies further demonstrated that inhibition of CTTN expression decreased tumor growth and lung metastasis." (PMID 32252688, 2020).